TNF (tumor necrosis factor)
Diseases named in the same sentence as TNF in open-access papers (continued):
Sharing a sentence is not in itself a finding about the gene and the disease.
depression (continued). "Hitherto, no meta-analysis has specifically compared the peripheral levels of proinflammatory markers including IL-1β, IL-6, TNF-α and CRP between elderly with depression or Alzheimer’s disease and controls without any psychiatric disorder." (PMID 30104698, 2018). "Meta-analyses have demonstrated that IL-6, TNF, and CRP are elevated in non-cancer patients with depression disorder." (PMID 30266081, 2018). "In AD patients without depression, the weak correlation observed between MMSE and IL 6 or TNF α were not statistically significant." (PMID 28580183, 2017). "Even though there are studies showing that people with depression have elevated levels of inflammatory biomarkers, such as TNF-alpha, IL-6, and CRP, inflammation is not necessary or sufficient for the diagnosis of depression." (PMID 26451727, 2015). "In a recent meta-analysis of allergy related cytokines in depression, IL1, IL4, IL6, and TNF-α, were found increased in depression compared to nondepressive study subjects and were considered to be a possible inflammatory link between the two disorders." (PMID 26783384, 2015). "After controlling for confounders, sIL-2R (but not TNF-α) significantly predicted FACIT scores (β = −0.31, p = .014), HAD depression scores (β = 0.36, p<.003), and HAD anxiety scores (β = 0.32, p<.008)." (PMID 23082161, 2012). "The aim of the study was to assess serum concentrations of TNF-α, TNF soluble receptors, leptin, and interleukin-6 (IL-6 ) in obese subjects with and without depression." (PMID 19587822, 2009). "Compared with non-depressed individuals, patients with depression show elevated levels of proinflammatory cytokines, including interleukin-1(IL1), interleukin-6(IL6), and tumor necrosis factor-alpha(TNF-α), as well as the systemic inflammation biomarker C-reactive protein(CRP)." (PMID 41179571, 2025). "Unlike the widely studied proinflammatory cytokines (IL-6, TNF-α, and CRP), these markers are rarely investigated in psychiatric research, despite their potential as indicators of both the metabolic and inflammatory background of depression." (PMID 40507778, 2025). "Finally, we did not directly measure TNF-α blood levels, nor did our PRS consider environmental factors, which also play an important role in the multifactorial nature of inflammation, depression, and cognitive performance." (PMID 38693319, 2024). "This intense stress can modulate changes in multiple pro-inflammatory cytokines, including interleukin-6 (IL-6) and tumor necrosis factor-α (TNF-α), leading to the appearance of depressive symptoms, such as sadness, lethargy, and lack of pleasure, and even to depression." (PMID 37781188, 2023). "However, in the present study no significant coevolution was found between IL-6, TNF-α, BDNF, and depression severity." (PMID 34841285, 2021). "Chronic GUO did not replicate the inhibitory effect on TNF-α release observed with acute GUO administration, or the anti-inflammatory effect obtained by subthreshold doses of GUO plus ketamine in mice submitted to a corticosterone model of depression." (PMID 34421682, 2021). "Regarding the entire sample in our results, we could not find a significant correlation between depression scores in DIKJ and TNF-α or IL-6-levels at baseline." (PMID 34204400, 2021). "On the association analysis between DNA methylation of miRNA coupled CpG-sites and HD, we performed multiple linear regression models of methylation M-values to HD and adjusted for depression, DST non-suppression status, CTQ total score and plasma levels of TNF-alpha." (PMID 31542994, 2020). "Nevertheless, human studies assessing the relationship between serum levels of pro-inflammatory cytokines (i.e., IL-6, INF-γ, TNF-α) and the anti-inflammatory lactoferrin with indicators of TRP metabolism in a large group of individuals with signs of depression are still lacking." (PMID 33312105, 2020).
depression (continued). "In general, TRD and drug-free patients had similarly increased levels of inflammation-related genes: this applied to both the genes that had been measured before in depression (IL1-beta, IL-6, TNF-alpha and MIF) and those never measured before (A2M, CRP, P2RX7, CCL2 and STAT1)." (PMID 32699209, 2020). "In addition, the levels of TNF-α, IL-Iβ and COX-2 were found to be not significantly different in the miR-301b mimic + SN50 and miR-301b mimic + PLX3397 groups, as compared with the depression and NC groups (p > 0.05)." (PMID 30962417, 2019). "However, we only tested one marker of inflammation (CRP) because other robust markers of inflammation (e.g., IL-6 and TNF-α) are not available in the NHANES data set, and the current utility of these inflammatory markers in depression is unclear." (PMID 30524737, 2018). "In a recent review of the connection between depression and inflammation, Krishnadas pointed out that a third of patients with major depressive disorder (MDD), without any other major illness, have elevated inflammatory biomarkers; in particular, CRP, TNF-α, and IL-6." (PMID 23898306, 2013). "rTMS increased serum BDNF levels and decreased serum IL-1b and TNF-a levels inpatients with depression but had no effecton any of these factors in healthy individualsResults suggest that rTMS may increase BDNF and decrease IL-1b and TNF-a serum levels in elderly patients with refractory depression." (PMID 35735405, 2022). "However, no studies have shown the relationship between aberrant TNF-alpha and suicidality in SCZ, but the results from the patients with depression could provide additional evidence." (PMID 31954374, 2020). "Our data suggests that marked alterations in the circulating levels of IL 6, TNF α and 25-hydroxyvitamin D result in severe AD with low MMSE and depression as the co-morbidity, while less dramatic changes of these parameters lead to AD with moderately low MMSE but without depression." (PMID 28580183, 2017). "Consistent with the suggestion that violent and/or impulsive behaviors may be linked to neuropsychiatric conditions, increased IL-1β, IL-6, and TNF-α in post-mortem PFC were observed in teenaged individuals that died by suicide, irrespective of whether they had been diagnosed with major depression." (PMID 25565946, 2014). "Similarly, the Genome-Based Therapeutic Drugs for Depression (GENDEP) project showed that the mRNA expression of inflammation-related genes, such as IL-1b, macrophage inhibiting factor (MIF) and tumor necrosis factor (TNF) are higher in non-responders depressed patients before treatment." (PMID 34103475, 2021).
Arthritis (1,540 papers, 2002 to 2026). Inflammation of a joint. "Firstly, both conditions involve chronic inflammation, with elevated pro-inflammatory cytokines like IL-6 and TNF-α exacerbating arthritis symptoms and contributing to CVD, a major cause of death in arthritis patients." (PMID 40904459, 2025). "Collectively, these results highlight the correspondence of ICI-arthritis myeloid cells to RA monocytic cells in defined pathogenic RA cell clusters and identify myeloid cell subsets that show evidence of co-stimulation by TNF and PGE2 in RA and ICI-arthritis." (PMID 40662950, 2025). "TNFα has long stood as a hallmark feature of both inflammatory bowel disease and arthritis with its therapeutic potential demonstrated in neutralizing monoclonal antibody treatments such as Infliximab." (PMID 39987456, 2025). "IL-1β, IL-6, IL-8, and TNF-α are small proteins associated with inflammation secondary to arthritis or disk disorders and have an important role in the onset and progression of TMDs." (PMID 40142185, 2025). "Homozygous TNF deletion completely abolished arthritis development, whereas heterozygous deficiency prevented disease onset in most cases." (PMID 41583484, 2025). "We also measured the serum levels of two crucial inflammation‐related cytokines, TNF‐α and IL‐6, which are intricately linked to arthritis pathogenesis." (PMID 40626319, 2025). "All controls as well as Rsk2−/y mice exhibited an intact cartilage layer (score 1), whereas the TNFα-overexpressing mice showed an advanced stage of arthritis with bony erosions, and erosions, and cartilage loss of more than 50% (score 5), and 75% (score 6)." (PMID 40140815, 2025). "Increased TNF expression in the synovial fluid in RA and the progression of arthritis in a TNF-α-transgenic mouse model revealed that TNF plays a pathogenic role in chronic inflammation." (PMID 39062908, 2024). "We have previously shown that SFs exclusively receive the pathogenic load of TNF to orchestrate the arthritic disease in modeled arthritis, such as the hTNFTg and TNFΔARE models or Collagen Antibody Induced Arthritis (CAIA)." (PMID 39122678, 2024). "Osteoclast-specific Atx knockout mice showed reduced bone loss in TNF-α-induced synovitis, lipopolysaccharide (LPS)-induced arthritis, and K/BxN serum transfer-induced arthritis models." (PMID 39744622, 2024). "Our study, therefore, contributes to the signaling map underlying SF responses in TNF-mediated arthritis that would inform potential therapeutic - strategies targeting SFs." (PMID 39122678, 2024). "Increased arthritis disease activity was associated with higher levels of inflammatory cytokines (IL-6, TNF and CRP) and immunoregulatory cytokine IL-10 (p<0.05)." (PMID 38507338, 2024). "PLN expansion persists to ~8-months of age in male TNF-Tg mice, followed by stochastic and asymmetric collapse of PLNs, associated with reduced volume and blood flow, and rapid onset of “Advanced” arthritis with severe synovitis and bone erosion." (PMID 37691918, 2023). "SKG arthritis symmetrically affects joints and is associated with the elevation of key RA cytokines including IL‐6, IL‐1β, and TNF." (PMID 36890657, 2023). "Arthritis-synovitis is a condition associated with lameness in cattle, and TNF-α is a proinflammatory cytokine responsible for the development of the inflammatory process and tissue damage." (PMID 36828912, 2023). "Through our spatial transcriptomics analysis, we identified down-regulation of Ferritin (Fth1) gene expression within the PLN sinuses of TNF-Tg mice with Advanced arthritis, which was associated with accumulation of iron-laden macrophages." (PMID 37691918, 2023). "Tumor necrosis factor alpha (TNF-α) is a well-characterized proinflammatory cytokine that plays a central role in several diseases with underlying inflammation such as arthritis and inflammatory bowel diseases." (PMID 35579886, 2022).
Arthritis (continued). "Excessive production of TNF-α is directly associated with several inflammatory disorders, such as arthritis and inflammatory bowel disease and the regulation can be an effective therapeutic strategy in these diseases." (PMID 36555275, 2022). "In humans, severe CHIKV arthritis is associated with elevated serum cytokine/chemokine levels, such as IL-1β, IL-6, TNF-α, CXCL10, etc.." (PMID 36377866, 2022). "In the four remaining patients (one with SAPHO, three with associated arthritis), methotrexate was insufficient to control the disease and add-on with a TNF-α blocker (etanercept) was necessary." (PMID 35698069, 2022). "TNF-α and IL-6 are key cytokines that drive inflammation in arthritis; TNF-α levels were elevated in patients with loss-of-function mutations in the DNase II gene, and both TNFα and IL-6 levels were high in DNase II−/−Ifnar1−/− mice." (PMID 34901991, 2022). "The depletion of GM-CSF was associated with greater disease suppression in arthritis models compared with TNF deprived controls." (PMID 35662723, 2022). "Second, anti-TNFα therapies carry an increased risk of infections, most notably reactivation of tuberculosis, as well as liver problems, arthritis, and lymphoma." (PMID 34679598, 2021). "In an animal model study on the influence of the absence of vitamin D signaling in chronic arthritis, clinical symptoms of arthritis were aggravated in the VDR-deficient human tumor necrosis factor (TNF) transgenic mice." (PMID 33669918, 2021). "Additional correlations showed that lower arthritis scores were associated with reduced overall immune infiltration, reduced myeloid cell representation among the infiltrate, and less TNF-α producing myeloid cells." (PMID 32966314, 2020). "It has also been observed that the serum levels of several arthritis-associated or inflammation-associated cytokines, such as TNF, IL-1β, IL-6, and monocyte chemoattractant protein-1 (MCP-1), were augmented." (PMID 32958016, 2020). "In the present study, we investigated the in vivo effects of Ang II on bone erosion and systemic bone loss in a tumor necrosis factor (TNF)-induced arthritis model." (PMID 32532031, 2020). "Nrf2 has antioxidant and anti-inflammatory activity, and its deficiency not only accelerates the progress of arthritis and joint destruction but also promotes the production of TNF-α, IL-1β, and IL-630." (PMID 32071294, 2020). "In an animal model of arthritis using human TNF-transgenic mice (hTNF-tg), cathepsin K deficiency inhibits osteoclast activation, preventing joint erosion and presenting a regulatory role on the immune system." (PMID 33330566, 2020). "Associating SNPs in specific genes with arthritis helps to associate genotypes and/or molecular types with prognosis or treatment responses, such as responses to TNF blocked." (PMID 32958016, 2020). "ELISA and qRT-PCR analysis showed that the induction of arthritis caused a significant increase in the levels of TNF-α, IL-1β, and IL-6 compared to the healthy group." (PMID 32401927, 2020). "On the other hand, genetic ablation of A20, PGRN, and CTRP6 increased the susceptibility of mice to experimental arthritis development by promoting NF-κB activation, TNFα-mediated inflammation and complement activation, respectively." (PMID 33270017, 2020). "In this study, we investigated the effects of the arthritis-associated cytokines IL-17 and TNF-α on the migration and invasion of FLS." (PMID 32414400, 2020). "We saw an arthritis-associated inflammation in case of static isotropic tensile strain, as the proinflammatory markers (TNF-α, IL-1β, IL-6, COX-2) were significantly upregulated." (PMID 32485947, 2020). "Blocking sclerostin by a monoclonal antibody in human tumor necrosis factor transgenic (hTNFtg) mice model of arthritis reduces loss of systemic bone mass, periarticular bone destruction and cartilage damage, without any effect on inflammation." (PMID 33330566, 2020).
Arthritis (continued). "Taken together, these results indicate that exposure to hallmark arthritis cytokines like TNF-α can partially mimic the CIA impact on MSC." (PMID 31683648, 2019). "In a TNF-transgenic arthritis model, SH3BP2 deficiency decreased joint destruction via direct suppression of osteoclastogenesis." (PMID 31052273, 2019). "During joint inflammation in experimental models of arthritis, up-regulated TNF in the spinal cord is implicated in increased articular nociception." (PMID 32038637, 2019). "In multivariate analysis, we confirmed female gender, longer disease duration, IBD-related surgery, presence of other EIM and treatment with anti-TNF to be independent risk factors for the onset of arthritis/arthralgia in CD and UC/IBDU patients." (PMID 31039159, 2019). "In adult patients with arthritis, use of the tumor necrosis factor (TNF) inhibitor etanercept (ETN) is often associated with a reduction in the utilization of co-medications, particularly steroids." (PMID 31500631, 2019). "TNF-alpha is involved in a number of autoimmune/inflammatory diseases and is one of the major proinflammatory factors in arthritis causing joint inflammation and cartilage destruction." (PMID 29850558, 2018). "Overexpression of TNF or enhanced IL-6 signaling due to a gain-of-function mutation of gp130 is sufficient to induce arthritis in mice." (PMID 30466479, 2018). "The systemic overexpression of TNF-α causes arthritis with subchondral erosions (in TNF-α transgenic mice)." (PMID 28753982, 2017). "Cytokines, such as TNF-α and IL-1β, are often associated with the progression and severity of arthritis." (PMID 28860993, 2017). "The results obtained for TNF involvement in the model were mixed, since arthritis developed in one-third of the TNF-deficient mice, indicating that TNF is an important, but dispensable, driver of disease development." (PMID 27313578, 2016). "In mice with a FcγRIIB-deficient C57BL/6 background, TNF-α is indispensable while IL-17 is dispensable in the pathogenesis of arthritis." (PMID 26634933, 2016). "In mouse models of arthritis, GM-CSF deficiency or neutralization prevented the development of arthritis and reduced the concentrations of TNF and IL-1 in joints." (PMID 29259681, 2016). "Pro-inflammatory cytokines, such as TNF, IL-1, and IL-6, are pathogenic drivers in both RA and in many mouse models of arthritis; however, the impact of each cytokine on the disease progression can differ from patient to patient and from model to model." (PMID 27313578, 2016). "Our previous study found that AR has anti-arthritic effects through PI3K/Akt signaling pathway and attenuating TNF-α associated collagen-induced arthritis." (PMID 27248986, 2016). "Another study from The South Swedish Arthritis Treatment Group register (SSATG) evaluated the risk of malignancy in patients who had undergone TNF inhibitor therapy." (PMID 27630714, 2016). "TNF is involved in a number of autoimmune /inflammatory diseases and is one of the major proinflammatory factors in arthritis causing joint inflammation and cartilage destruction." (PMID 26086874, 2015). "The events that underline the progression of arthritis are mediated by several chemotactic factors such as interleukins (IL-1, IL-6, and IL-10), tumor necrosis factor (TNF-α), interferons (INF-γ) plus leukocytes, and adhesion factors." (PMID 26273477, 2015). "TNF-Tg mice that we generated to be deficient in p100 have significantly accelerated development of arthritis and systemic bone loss, suggesting that p100 not only limits OC formation, but also joint inflammation induced by TNF." (PMID 26287732, 2015). "Intra-articular injection of SPION during experimental arthritis caused a minor upregulation of TNFα and IL-1β gene expression in the synovium at 2 days after injection, which was on the 5th day of the AIA model." (PMID 25955417, 2015).